RNU5A-6P (RNA, U5A small nuclear 6, pseudogene)
Gene: Small nuclear RNA gene on chromosome 18 (24,124,170 to 24,124,285, reverse strand). Ensembl gene ENSG00000206863.
Homologues: Orthologues: chimpanzee U5 (96% identical), macaque U5 (93% identical), rabbit U5 (84% identical), mouse Gm23102 (66% identical). Paralogues in human: RNU5E-5P (78% identical), RNU5E-4P (77% identical), RNU5E-7P (76% identical), RNU5E-10P (75% identical), RNU5A-4P (74% identical), RNU5A-2P (73% identical), RNU5E-8P (73% identical), RNU5A-5P (72% identical), RNU5B-4P (72% identical), RNU5F-7P (72% identical), RNU5A-7P (72% identical), RNU5E-6P (71% identical), and 13 more.